PLAGL1 (PLAG1 like zinc finger 1)
Diseases named in the same sentence as PLAGL1 in open-access papers (continued):
Sharing a sentence is not in itself a finding about the gene and the disease.
cancer (18 papers, 2012 to 2025). A tumor composed of atypical neoplastic, often pleomorphic cells that invade other tissues. "Although its specific role in tumorigenesis is controversial and its functions appear to depend on the cellular context, altered expression of PLAGL1 has been linked to various types of cancer." (PMID 34355256, 2021). "Removal of PLAGL1 TFBS in subjects harbouring the rs368234815 ∆G allele may contribute to cancer susceptibility." (PMID 33482747, 2021). "Moreover, GSEA of cancer gene neighborhoods, defined by the expression domains of 380 cancer-related genes, suggested that PLAGL1 was associated with cell cycle and cell proliferation operation related genes, which had significant P values and high normalized enrichment scores." (PMID 36600208, 2023). "The downregulation of PLAGL1 in our analysis is in line with this observation, so its role in the cancer degeneration of heterotopic gastric areas cannot be excluded." (PMID 34715892, 2021). "Previously, studies in murine and human prostate tissue and cancer detected a transcriptional network of co-regulated imprinted genes, with PLAGL1 as putative key player." (PMID 30297886, 2018). "CLU is overexpressed in several cancers and has been shown to inhibit apoptosis by interfering with Bax activation in mitochondria, while PLAGL1 is a tumor suppressor protein, which concurrently induces apoptosis and cell cycle arrest." (PMID 26573568, 2015). "Even if PLAGL1 is frequently altered in various cancer types, to date, no study has extensively investigated the possible prognostic role of PLAGL1 promoter methylation status in STS and its possible association with cancer patient outcome." (PMID 24260468, 2013). "Additionally, upregulated genes included H19, IGF2 and DLK1, all regulated by PLAGL1 and with known functions in tumorigenesis of different cancers." (PMID 34355256, 2021). "PLAGL1 gene is often deleted or methylated and silenced in cancer cells." (PMID 33482747, 2021). "Additionally, upregulated genes of potential interest included H19 and IGF2 (adjusted p = 1.31e − 83, adjusted p = 5.04e − 08), both regulated by PLAGL1 and with known functions in the tumorigenesis of different cancers." (PMID 34355256, 2021). "Nonetheless, the role of PLAGL1 in cancer has been controversial." (PMID 33392508, 2020). "In addition, GSEA of cancer gene neighborhoods also suggested that multiple genes in the gene set correlated with PLAGL1 could regulate cell proliferation as well." (PMID 36600208, 2023). "Of the top down-regulated genes, PLAGL1, CTH and VIM are positively correlated with HNSCC, while increased expression of RMRP, SULT1 and LTBP1 has been recorded in other cancers." (PMID 31827722, 2019). "Additionally, genes such as EEF1A2 (protein synthesis and cancer cell survival), RAMP2 (cardiovascular homeostasis), PLAGL1 (cell growth suppression and differentiation activation), and STRIP2 (stem cell differentiation and cell morphology regulation) were also suppressed." (PMID 40427555, 2025).
CNS tumor (8 papers, 2021 to 2025). "Through our screening, we identified a subset of CNS tumors (n=12) epigenetically distinct from other known CNS tumor types, but clustering close to the PLAGL1- and PLAGL2-amplified ET, PLAGL subtypes in our t-SNE analysis." (PMID 40751809, 2025). "Some of these EWSR1 rearrangements are fusions with the PLAGL1 gene, and other PLAGL1 gene rearrangements in CNS neoplasms have also been described." (PMID 38639853, 2024). "In keeping herewith, we show through ChIP-seq data that components of the Wnt-pathway such as FZD2 and FZD9 are direct targets of PLAGL1 and PLAGL2 and are overexpressed in the PLAGL1/2-amplified samples compared to the other CNS tumor types." (PMID 36437415, 2023). "In a single case, PLAGL1 was fused to EP300, a fusion partner known from ‘CNS tumors with BCOR alteration’." (PMID 34355256, 2021). "By t-SNE dimensionality reduction of DNA methylation profiles, PLAG1-fused tumors show a methylation pattern closely related to the one characteristic of PLAGL1- and PLAGL2-amplified tumors, but otherwise epigenetically distinct from all other described CNS tumor types." (PMID 40751809, 2025). "We describe a biologically distinct pediatric CNS tumor type (n = 31 cases) that is characterized by focal high-level amplification and resultant overexpression of either PLAGL1 or PLAGL2, and an absence of recurrent genetic alterations characteristic of other pediatric CNS tumor types." (PMID 36437415, 2023).
PLAGL1 also shares sentences with these, for which no sentence is quoted: CNS embryonal tumor (3 papers); supratentorial ependymoma (3); anaplastic ganglioglioma (2); chorioamnionitis (2); alveolar rhabdomyosarcoma (1); asthma (1); autism (1); basal cell carcinoma (1); Beckwith-Wiedemann syndrome (1); colon cancer (1); diffuse astrocytoma (1); diffuse large B-cell lymphoma (1); diffuse midline glioma (1); ependymal tumor (1); Fanconi anemia (1); fibrosarcoma (1); ganglioglioma (1); head and neck squamous cell carcinoma (1); head and neck tumor (1); insulin-resistant (1); medulloblastoma (1); mesenchymal tumors (1); metabolic disorders (1); neurological diseases (1); non-alcoholic fatty liver disease (1); oligodendroglioma (1); ovarian tumor (1); pancreatic adenocarcinoma (1); pituitary tumor (1); pleomorphic xanthoastrocytoma (1).
A further 10 diseases each share a sentence with PLAGL1 in 1 paper.